CD4 (CD4 molecule)
Diseases named in the same sentence as CD4 in open-access papers (continued):
Sharing a sentence is not in itself a finding about the gene and the disease.
COVID-19 (continued). "Taken together, these results demonstrate that in COVID-19 there is an induction of the CD4+ T-lymphocyte cytotoxic response in severe/critical cases." (PMID 36359755, 2022). "Here, we present a longitudinal analysis of the SARS-CoV-2-specific CD4+ T-cell response in two COVID-19 patients." (PMID 35746736, 2022). "Recent studies have shown that increased activation and exhaustion of memory B cells observed during COVID-19 correlates with CD4+ T cell functions, and consistent with this, we observed reduced CD4+ EM cell proportions in COVID-19 convalescents at 12 wpi." (PMID 35027067, 2022). "Among hospitalized and community COVID-19 cases (prioritized sample set), we found the principal components of variance in gene expression involved cMono, naive B cells, plasmablasts, CD4+ T cells (naive, effector, and effector memory), and cycling NK cells." (PMID 35216673, 2022). "Recent data showed that the recovered COVID-19 patients have displayed, weeks after symptoms appeared, an immune response carried out by response of T cells CD4+ and CD8+." (PMID 35237261, 2022). "We observed a significant increased level of LAG-3+CD4+ T cells among COVID-19 patients at hospitalization and again at the 6-7 month time point when compared to healthy controls." (PMID 36003367, 2022). "To date, treatments with the objective to improve the quantity and quality of CD4+ T cells in COVID-19 have focused on addressing hyperactivation, anergy, or modulating specific cytokines, such as IL-1 and IL6." (PMID 36678366, 2022). "Cellular deconvolution analysis using modified Housman’s method detected six cell-types, namely NK, CD8+ T, CD4+ T, B cells, neutrophils, and monocytes, which were present in both convalescent COVID-19 individuals and controls." (PMID 35464396, 2022). "Significant decreases in CD4+ T cells, total T cells, and B cells were observed in critical COVID-19 patients." (PMID 36403042, 2022). "It is noteworthy that patients with critical COVID-19 who are admitted to the ICU usually present CD4+ cytopenia, which makes it difficult to develop a complete, effective immune response against SARS-CoV-2." (PMID 35401523, 2022). "It has been found that SARS-CoV-2-specific circulating Tfh cells (cTfh) were a substantial fraction of the SARS-CoV-2-specific CD4+ T cells in acute and convalescent COVID-19 patients." (PMID 34975340, 2022). "In the present study, we confirmed the decreased lymphocyte count observed in severe COVID-19 patients affecting both CD4 + and CD8 + T cells." (PMID 35246776, 2022). "While comparably expressed in activated CD4+ T cells across acute COVID-19 cases, these markers increased in CD8+ T cells with increasing disease severity." (PMID 35216673, 2022). "Stimulation with N induced differences in the overall polyfunctionality of CD4+ T cells between patients who recovered (moderate vs. severe) and between COVID-19 severe patients and those who recovered from severe disease." (PMID 35887351, 2022). "To date, multiple studies have shown that COVID-19 vaccination elicits a stable and fully functional CD4+ and CD8+ T cell response that is maintained across different vaccine platforms (e.g. mRNA-1237, BNT162b2m Ad26.CoV2.S and NVX-CoV2373) and VOCs." (PMID 36618413, 2022). "Similar results were obtained using molecular biological research methods: the expression of Th17-associated genes (RORC, IL17A, IL17F, and CCR6 decreased in the peripheral blood CD4+ T cells from patients with severe COVID-19." (PMID 35632823, 2022). "While CD73 expression is a hallmark of CD8+ T-cells with reduced functionality in COVID-19, in HIV infection, CD73 expression in CD4+ and CD8+ T-cells has been shown to be associated with elite control." (PMID 35746736, 2022). "For this reason, some COVID-19 vaccination efforts are focused on elicitation of CD4+ or CD8+ T-cells." (PMID 36474011, 2022).
COVID-19 (continued). "The increased vascular superoxide production with endothelial dysfunction, defective CD4+ and CD8+ T-cells and the impaired complement system in diabetic patients make this group more susceptible to poor outcomes in the course of COVID-19." (PMID 35160324, 2022). "Our data are in line with other studies in which a higher representation of activated (CD69+) interferon-γ-producing CD4+ T-lymphocytes was detected in hospitalised COVID-19 patients with pneumonia." (PMID 36366522, 2022). "Cytokine profiling demonstrated predominant Th1 polarization of CD4+ T cells from children with convalescent COVID-19 and MIS-C, although cytokine production was reduced in MIS-C." (PMID 35044955, 2022). "Several studies suggest that increased severity of COVID-19 induces a stronger SARS-CoV-2-specific CD4+ T cell response." (PMID 35185909, 2022). "According to our data, convalescent patients with mild and moderate COVID-19 formed a broad spectrum of SARS-CoV-2-specific CD4+ T cell subsets, but they predominantly expressed CCR6 and were capable of inducing type 3 immunity on mucosal tissues." (PMID 36146622, 2022). "The HIV-positive patients who became infected with COVID-19 had a lower mean CD4+ lymphocyte count compared to prior COVID-19 infection." (PMID 35371792, 2022). "Induction of CD4+ and CD8+ T cell-mediated immunity, another fundamental arm of the adaptive immune system, has been associated with reduced COVID-19 disease severity, but is far less well characterized than humoral reactivity to SARS-CoV-2 vaccination." (PMID 36618413, 2022). "COVID-19 or vaccination with S leads to the generation of S-epitope-specific memory CD4+ TH cells and circulating follicular TH cells that rapidly expand upon re-exposure to the S antigen." (PMID 35632675, 2022). "In contrast, the CD4 T-cell responses towards the S protein were boosted in vaccinated groups with previous COVID-19, suggesting an immune enhancer effect on the T-cell responses." (PMID 36139625, 2022). "SARS-CoV-2-specific CD8+ T cells are also detectable in acute COVID-19 cases, albeit less consistently than CD4+ T cells, and their presence was also correlated with a better outcome of COVID-19." (PMID 35992306, 2022). "The majority of SARS-CoV-2–specific CD4+ T cells produced at least 2 cytokines, and IL-2+TNF-α+ SARS-CoV-2–specific CD4+ T cells were the dominant subpopulation of the COVID-19 immune landscape." (PMID 35230977, 2022). "This indicates that COVID-19 patients with a decreased T-cell response, including CD4+ and CD8+ T-cells, are likely to be more vulnerable to disease severity and fatality, highlighting the central role of CD4+ and CD8+ T-cells in SARS-CoV-2 clearance." (PMID 36389664, 2022). "The CD4+ Treg absolute numbers in pediatric COVID-19 have been recently described and our study also revealed similar findings of decreased absolute numbers of Treg." (PMID 36322537, 2022). "Previous data show that there is an increase in activated CD4+/CD8+ T lymphocytes in the lungs of critical COVID-19 patients." (PMID 36027872, 2022). "From convalescent COVID-19 patients, CD4+ T cell responses strongly correlated to anti-SARS-CoV-2 IgG and IgA titres." (PMID 36045689, 2022). "In future studies, the size of the naïve TCR repertoire which correlates with the pool size of CD4 T cells would be an interesting parameter to measure in COVID-19 clinical studies." (PMID 36078151, 2022). "In total, 250 aggregate next-generation sequencing libraries, one each for CD4+ and CD4− fractions, were constructed and analyzed, including some longitudinal samples primarily from patients with active COVID-19." (PMID 35943978, 2022). "Another study found lower IFN-γ secretion by CD4+ T cells in severe COVID-19 patients than in moderate patients." (PMID 36363785, 2022). "The close connection between CD4+ T cells and antibody production in COVID-19 convalescent patients has been demonstrated." (PMID 35844601, 2022).
COVID-19 (continued). "Vaccinated subjects and post-COVID-19 patients showed comparable and sustained levels of specific CD4+ proliferative response at early and late time points, with no significant decrease." (PMID 35744768, 2022). "PLWH have been disproportionately affected by COVID-19 and are at increased risk for severe clinical symptoms and mortality due to SARS-CoV-2 infection, especially among those with lower CD4+ T cell counts or detectable HIV viremia." (PMID 36286201, 2022). "A higher number of CD4+ cells expressing GM-CSF and IL-6 was reported in COVID-19 patients admitted to intensive care units." (PMID 36034704, 2022). "A CD4+ T-cell count ≥ 350 decreased the probability of contracting COVID-19 by 1·317 times (95% CI: 1·155–1·502)." (PMID 35340627, 2022). "In another cohort of five COVID-19 patients and seven matching healthy controls, the same analysis was performed on CD4+ T cells." (PMID 36290721, 2022). "The saRNA groups had the highest proportion of spike specific CD8+ cells relative to CD4+ cells (CD8+:CD4+ ratio GM 0.75 (sd±2.6) and 1.3 (sd±3.1) in COVID-19 naïve and previously infected respectively)." (PMID 36194628, 2022). "In a linear regression analysis, we observed increased CD4+ macrophage density in COVID-19 autopsy samples to be strongly correlated with decreased density of alveolar epithelial cells." (PMID 35446789, 2022). "Illumina data has been uploaded to SRA under the BioProject accession: PRJNA705196 CD4+ T Cell Receptor Sequencing of COVID-19 Convalescent, Vaccinated, or Pre-COVID Healthy Donors." (PMID 35533495, 2022). "COVID-19 patients exhibited significantly low CD4+ lymphocyte expansion and leucocytosis augmented by elevated neutrophil and immature granulocytes." (PMID 35980979, 2022). "The pro-inflammatory cytokine levels were elevated in severe COVID-19 patients, but it is observed that both Treg and IL-10-expressing CD4+ T, CD8+ T and NK cells levels were gradually increased from mild to severe patients." (PMID 36110850, 2022). "Similar to COVID-19, lymphopenia affecting CD4+ (helper T) cells, CD8+ (cytotoxic T) cells and γδ T cells was observed at the beginning of the acute phase of MIS-C." (PMID 35466278, 2022). "We have investigated the association between memory CD4 and CD8 T cells and levels of neutralizing antibodies in convalescent COVID-19 subjects." (PMID 36544780, 2022). "used T-cell receptor (TCR)-dependent activation induced marker (AIM) assays to identify and quantify SARS-CoV-2-specific CD4+ T cells in recovered COVID-19 patients." (PMID 36389144, 2022). "Broncho-alveolar lavage fluid from patients with severe COVID-19 has shown a predominance of neutrophils, monocytes/macrophages, and eosinophils with few lymphocytes, and in particular CD4 and CD8 T-cell lymphopenia, but an increase in the proportion of Tregs." (PMID 35224470, 2022). "Because the CD4-to-CD8 ratio and neutrophil-to-CD8 ratio have been identified as reliable risk factors for predicting COVID-19 mortality, we further analyzed T-cell subsets." (PMID 36222118, 2022). "It is but natural that the decreased numbers and impaired functions of CD4+ T cells, NK cells, DCs and phagocytes as observed in COVID-19 are likely to impair the immune response against fungal invasion." (PMID 35111359, 2022). "In patients with COVID-19, lymphopenia, including decreased CD4 and CD8 T cells, B cells, and NK cells, has been observed, although the breadth of immune cells that SARS-CoV-2 impacts is not consistent across all individuals." (PMID 36297092, 2022). "When patients recover from COVID-19, they often exhibit strong and specific CD4+ T cell responses that are similar to what has been seen with influenza virus infection." (PMID 36034704, 2022). "A number of studies early in the pandemic identified SARS-CoV-2 specific CD4 T cells in COVID-19 patients." (PMID 36544780, 2022).
COVID-19 (continued). "In contrast, ketogenesis was impaired in moderate to severe COVID-19 and a deficit in the production of interferon-γ and other interferon-related cytokines by CD4+ T cells was found." (PMID 36615679, 2022). "Second, like other COVID-19 neuropathologic studies, inflammatory changes including the presence of microglial nodules, neuronophagia, and microgliosis with some degree of CD4 + and CD8 + T lymphocytes infiltrating in meninges were observed in six decedents." (PMID 36528671, 2022). "Studies of COVID-19 patients have observed that adaptive immune response limits COVID-19 disease severity and balanced CD4+ T cell, CD8+ T cell, and antibody responses are protective, significantly associated with milder disease." (PMID 34975340, 2022). "Data from the AIM assay showed that participants in the non-saRNA group receiving mRNA vaccination only (both those convalescent and naïve for COVID-19) had greater CD4+ T cell responses than CD8+ T cell responses." (PMID 36194628, 2022). "Oncologic patients with previous COVID-19 followed by vaccination exhibited potent IL-17+ CD4 and CD8 T-cell responses and elevated numbers of circulating neutrophils in peripheral blood." (PMID 36139625, 2022). "The present study found that CD4+ cell count significantly reduced in severe COVID-19 cases compared to mild ones, which affects the severity of lung involvement and prognosis of the disease." (PMID 35930526, 2022). "Patients who died of COVID-19 had a median CD4+ lymphocyte count of 134 (n = 18) (IQR: 30–248) and mean World Health Organization (WHO) clinical stage of 3.2 (s.d.: 0.79)." (PMID 35419453, 2022). "A similar immune response is observed in patients with COVID-19, with reduced CD4+ T cell counts and increased Th17 cell counts." (PMID 35888567, 2022). "Albeit of above limitations, our findings still give the hint that future COVID-19 vaccines need to consider CD4+ T cells, cTfh1 and antibodies to achieve long-term protective immunity." (PMID 35461307, 2022). "Nadir CD4 count during the subsequent COVID-19 illness was 573 cells/μl (23% of lymphocytes) and lowest CD4/CD8 ratio 0.47 2 days after hospitalization." (PMID 34625910, 2022). "RNA-Seq of severe COVID-19 patient blood samples showed a significant elevation of leukocyte CD4+ T cells compared to uninfected controls." (PMID 35897696, 2022). "Recently it has been shown that COVID-19 vaccine-induced CD4-CTLs recognize viral antigens in a major histocompatibility complex (MHC) class II dependent manner." (PMID 36353619, 2022). "Regarding the effector capacity, we observed that despite similar frequencies of vaccine-induced CD4+ T cells at month 8, individuals who have recovered from COVID-19 produced significantly more IFN-γ following stimulation with spike than naive individuals." (PMID 35139036, 2022). "One possible factor for this progression is the CD4+ T cells which are the key immune defenders against mycobacterium tuberculosis (Mtb) but unfortunately found to be exhausted and reduced in COVID-19 patients." (PMID 35242137, 2022). "Circulating SARS-CoV-2-specific CD8+ and CD4+ T cells were identified in ~70% and 100% of patients with COVID-19 and spike-specific responses positively correlated with anti-SARS-CoV-2 IgG titers." (PMID 35062730, 2022). "In severe COVID-19 patients, the exhaustion marker PD-1 was highly expressed in CD4+ and CD8+ cells." (PMID 36369012, 2022). "The fraction of CD38+HLA-DR+ activated CD4+ T cells in the COVID-19 patients significantly decreased over the study duration and appeared to be lower than healthy controls at 6-7 months although this was not significant." (PMID 36003367, 2022). "COVID-19-induced lymphopenia affected all T lymphocyte subsets as both CD4 + and CD8 + T cell numbers were markedly decreased in patients at D0." (PMID 35246776, 2022).
COVID-19 (continued). "Absolute lymphocyte count was also low in SOT COVID-19 patients and our methylome analysis corroborated these findings with low/undetectable cfDNA levels from CD4+ T cells and CD8+ T cells." (PMID 35075453, 2022). "We previously identified the 17-mer peptide S813-829 to be targeted by CD4+ T cells in some COVID-19 mRNA vaccine recipients." (PMID 35061630, 2022). "A similar decrease is characteristic of long COVID-19 patients who presented lower CD4+ T cell counts, compared to other groups of patients." (PMID 35335635, 2022). "In a retrospective study including 76 patients with severe COVID-19, Tα1 treatment significantly reduced patient’s mortality (P < 0.05) and increased CD4+ and CD8+ T cell counts compared with the control group." (PMID 36567402, 2022). "In individuals with COVID-19, CD4+ T cells expressed significant amounts of inflammatory genes, including JUN." (PMID 37521843, 2022). "The reduction in type I INF production, the increase in proinflammatory monocytes and the accumulation of functionally exhausted and senescent CD4/CD8 T cells is similar between the immune profiles of severe COVID-19 patients and healthy older adults." (PMID 36365007, 2022). "SARS-CoV-2 induced an overexpression of PD-L1 in epithelial cells, and it was dysregulated in a variety of immune cells including neutrophils, gamma delta T cells, monocytes, and CD4+ T cells of COVID-19 patients." (PMID 35432324, 2022). "Another study found an association between CD4+ T cells expressing programmed cell death protein-1 (PD-1 or CD279) and APACHE III scores in patients with COVID-19." (PMID 35632823, 2022). "To assess the exhaustion phenotype in critically ill patients with COVID-19, we verified an increase in the frequency of CD4+ and CD8+ T cells that express PD-1 in severe/critical patients compared to uninfected individuals." (PMID 36359755, 2022). "Next, we assessed the short-term longitudinal effect of CD24Fc treatment on CD4+ T cells in COVID-19 patients." (PMID 35012610, 2022). "In our cohort, patients who survived COVID-19 were younger, had a longer duration of symptoms before admission to hospital and higher levels of predicted naïve CD4+ T cells and naïve B cells." (PMID 35663963, 2022). "A study of 499 COVID-19 patients reported that 95% of patients in the ICU group exhibited a decrease in both CD4/CD8 T cells, in addition to high expression of PD-1 and Tim-3 exhaustion markers on their T cells." (PMID 36365007, 2022). "We observed that children with COVID-19 had an increased frequency of CD4+ T cells positive for the expression of ROR-γt compared with healthy donors (p<0.05)." (PMID 35663467, 2022). "In another study involving flow cytometry-based PBMCs analysis from moderately to severely ill COVID-19 patients, around 1.4% and 1.3% virus-specific CD4+ and CD8+ T cells, respectively, were detected in all patients post 15 days ICU admission." (PMID 35883618, 2022). "These circulating virus-specific CD4+ T cells were identified in 100% of patients recovered from COVID-19." (PMID 36146622, 2022). "Representative dot-plots illustrate the comparison of CD3+CD4+ T cells expressing PD-1 in blood samples treated with polyclonal stimuli from participants who developed mild or severe COVID-19 during the follow-up." (PMID 35860236, 2022). "FOSB inactivation in mast cells has been shown to increase the inflammatory response, and it has contradictorily also been reported to be upregulated in single cell analysis of CD4+ T-cells of severe COVID-19 patients." (PMID 35438176, 2022). "In contrast, we observed shifts in decreasing plasmablasts percentage, and increasing CD4+ naïve T cells were observed in those under 50 years of age following COVID-19." (PMID 35719387, 2022).